PIEZO1 (piezo type mechanosensitive ion channel component 1 (Er blood group))
Diseases named in the same sentence as PIEZO1 in open-access papers (continued):
Sharing a sentence is not in itself a finding about the gene and the disease.
melanoma (continued). "The results indicated that phosphorylation of AKT and mTOR were decreased in melanoma cells after knockdown of Piezo1." (PMID 36112948, 2022). "Our results showed that knockdown of Piezo1 suppressed the viability of melanoma cells and decreased the expression of Cyclin D1 and CDK2." (PMID 36112948, 2022). "The results suggested that the Piezo1 ion channel protein was functional in melanoma cells and modulated intracellular calcium concentration." (PMID 36112948, 2022). "The aim of this study is to clarify the role of Piezo1 and its potential mechanism in regulating the malignant phenotypes of melanoma." (PMID 36112948, 2022). "Piezo1 mRNA expression level was upregulated in melanoma compared with normal skin tissues in TCGA database." (PMID 36112948, 2022). "Here, we first demonstrated Piezo1 mechanosensitive ion channel in promoting tumor aggression in melanoma." (PMID 36112948, 2022). "In the present study, we first showed that Piezo1 was abnormally expressed in melanoma, which accelerated the malignant progression by activating AKT/mTOR signaling." (PMID 36112948, 2022). "In summary, we investigated the oncogenic role of Piezo1 in melanoma and demonstrated the mechanism which Piezo1 regulated malignant progression of melanoma through the PI3K/AKT/mTOR signaling pathway." (PMID 36112948, 2022). "To confirm the role of Piezo1 in melanoma cells, we constructed relevant cells for the following experiments." (PMID 36112948, 2022). "In the present study, we showed that Piezo1 was abnormally expressed in melanoma, which accelerated the malignant progression." (PMID 36112948, 2022). "We therefore conclude that Elkin1 supports a PIEZO1-independent mechanoelectrical transduction pathway and modulates cellular adhesions and regulates melanoma cell migration and cell-cell interactions." (PMID 32228863, 2020). "Similarly, our data indicate that melanoma cells respond to confinement by increasing stiffness in a PIEZO1-dependent manner, pointing to a conserved adaptive mechanism." (PMID 40890143, 2025). "Similarly, in the case of melanoma, Piezo1 promotes the malignant progression of the disease through Akt/mTOR signaling." (PMID 38690080, 2024). "Therefore, Piezo1 acts as an oncogene in melanoma cells and provides a novel candidate for melanoma diagnosis and treatment." (PMID 36112948, 2022). "Additionally, Piezo1 knockdown significantly weakened intracellular calcium signal and viability of melanoma cells." (PMID 36112948, 2022). "Furthermore, examining the protein abundance data in primary and metastatic cells derived from the same CRC and melanoma patient, we highlighted that cells derived from lymph-node metastases showed consistently downregulated expressions of Piezo1." (PMID 36080197, 2022). "To further clarify whether the function of Piezo1 in regulating the malignant progression of melanoma was directly dependent on the PI3K/AKT/mTOR pathway, we treated wild-type A375 cells with the PI3K inhibitor LY294002, the Piezo1 activator Yoda1 and both." (PMID 36112948, 2022). "It seemed that the aberrant expression of Piezo1 could influence the malignant behavior of melanoma." (PMID 36112948, 2022). "According to the function the Piezo1 mechanosensitive ion channel in melanoma, it may be a potential target for drug designed against cancer progression." (PMID 36112948, 2022). "Piezo1 was widely overexpressed in melanoma cells, and it could promoted proliferation, invasion, metastasis, transendothelial migration and distant metastasis in vitro and in vivo." (PMID 36112948, 2022). "To further investigate the possible mechanism of Piezo1 on malignant behavior of melanoma, we analyzed several possible candidates that respond to mechanical biosignalling pathways by the online bioinformatics GEPIA websites and found that Piezo1 was associated with AKT." (PMID 36112948, 2022).
melanoma (continued). "Therefore, our study clarified the novel function of Piezo1 in melanoma cells and provided a novel candidate for melanoma diagnosis and treatment." (PMID 36112948, 2022). "Therefore, the potential role of Piezo1 in the migration and invasion capacity of melanoma cells was explored." (PMID 36112948, 2022). "Since DNA replication activity is usually considered to represent proliferation capacity and determined by cell staining with Ki67 antibody, these results indicated that Piezo1 inhibition could suppress melanoma cell viability." (PMID 36112948, 2022). "According to the biology of melanoma, we first analyzed the expression level of Piezo1 in melanoma." (PMID 36112948, 2022). "We found that chemical activation of Piezo1 by its agonist, Yoda1, prevents melanoma spheroid formation; thus, Piezo1 could be a potential target for selective modulation aimed at the prevention of melanoma development." (PMID 37958687, 2023). "However, melanoma cell chemotaxis through a 3D collagen matrix or transmigration through synthetic pores is unaffected by GsMTx4-mediated inhibition of stretch-activated channels such as Piezo1." (PMID 35274124, 2022). "Moreover, the role of Piezo1 in melanoma was verified in vivo." (PMID 36112948, 2022). "However, it remains unclear how Piezo1 regulates malignant progression in melanoma." (PMID 36112948, 2022). "Piezo1 ion channel protein can regulate calcium concentration in melanoma cells, further increasing the activation level of the PI3K/Akt/mTOR pathway, thereby regulating the malignant progression of melanoma." (PMID 38690080, 2024). "Among them, PI3K/AKT/mTOR pathway regulates the invasion and metastasis process of melanoma upon activation by Piezo1, and the expression of EMT-related genes and invasion and metastasis-related genes (MMP2 and MMP9) in cells changes with the alteration of Piezo1 expression." (PMID 38690080, 2024).
myocardial infarction (9 papers, 2021 to 2026). Gross necrosis of the myocardium, as a result of interruption of the blood supply to the area, as in coronary thrombosis. "This work identifies fine‐tuning the expression of PIEZO1 as a critical molecular mechanism underlying the treatment of myocardial infarction by mechanically adapted cardiac patches, which can support the clinical translation of cardiac patch devices." (PMID 40344385, 2025). "Elevated expression of the mechanosensitive ion channel PIEZO1 in response to abnormal mechanical stimuli is implicated in many diseases, including myocardial infarction (MI)." (PMID 40344385, 2025). "Studies have shown that Piezo1‐mediated neurogenic inflammatory cascade exacerbates ventricular remodeling after myocardial infarction." (PMID 41488471, 2026). "Piezo has also been considered a candidate as Piezo1 is found in the vertebrate cardiovascular system and has been shown to be upregulated upon myocardial infarction." (PMID 36187790, 2022).
neuroblastoma (9 papers, 2017 to 2026). Neuroblastoma (NB) is the most common solid, extracranial childhood tumor. "Piezo1, encoded by FAM38A, was identified using small interfering RNA (siRNA) knockdown screening in the mouse Neuro2A neuroblastoma cell line." (PMID 33935792, 2021). "Despite a proven role for PIEZO1 in the neuromodulation of the neuroblastoma cell line, its efficiency and safety in (pre-)clinical studies have not been measured to date." (PMID 36765838, 2023). "PIEZO1, a kind of ionic channel protein, was first identified and described in a mouse neuroblastoma cell line." (PMID 36765838, 2023). "To test this finding, we first used the Neuro-2a (N2a) mouse neuroblastoma cell line since these cells natively express Piezo1 and were reported to conduct a Piezo1-dependent current in the presence of ssRNA40." (PMID 36382883, 2022). "In 2010, Patapoutian and colleagues discovered in a mouse neuroblastoma cell line a new gene, Fam38A, now known as Piezo1, which coded for a mammalian MS cation channel." (PMID 32635333, 2020). "The Piezo1 protein (also known as Fam38a) was identified to form the mechanically activated ion channel mediating pressure-induced ionic currents in mouse neuroblastoma Neuro2A cells." (PMID 31780935, 2019). "In 2010, using small interfering RNA (siRNA)‐mediated candidate gene silencing and whole‐cell patch‐clamp electrophysiology to record the MA cationic current, Piezo1 (also known as Fam38A) was identified as being responsible for mediating endogenous MA currents in neuroblastoma (Neuro2a) cell lines." (PMID 40781923, 2026). "Such glass pipette-induced force has been widely used in the study of Piezo1 channels in HEK 293T cells and a mouse neuroblastoma cell line." (PMID 28416610, 2017).
osteosarcoma (9 papers, 2020 to 2025). A usually aggressive malignant bone-forming mesenchymal neoplasm, predominantly affecting adolescents and young adults. "Mechanosensitive ion channel Piezo1 was discovered in mesenchymal tumors such as osteosarcoma (OsS) and synovial sarcoma (SynS)." (PMID 36837670, 2023). "The association between aggressive sarcomas such as synovial and osteosarcoma and Piezo1 expression was also demonstrated." (PMID 36837670, 2023). "In osteosarcoma, Piezo1-shRNA was found to inhibit invasion of osteosarcoma cells, and the Piezo1 protein may be a new, potential therapeutic target." (PMID 38690080, 2024).
pancreatic cancer (9 papers, 2022 to 2026). "In pancreatic cancer, overexpression of Piezo1 is closely associated with tumor malignancy, drug resistance, and poor patient prognosis." (PMID 41195420, 2025). "In pancreatic cancer models, Piezo1 has been shown to promote CTCs colonization in the liver and lungs and increase the survival ability of metastatic sites by interacting with immune cells." (PMID 41195420, 2025). "Silencing PIEZO1 suppresses the proliferation, migration, and invasiveness of pancreatic cancer cells." (PMID 40977743, 2025). "PIEZO1 is overexpressed in pancreatic cancer tissues compared to normal pancreas, and its high expression correlates with a poor prognosis for patients." (PMID 40977743, 2025). "Studies have demonstrated that Piezo1 can induce the apoptosis of pancreatic cancer cells, pneumocytes and nucleus pulposus cells, and the inhibition of Piezo1 can treat apoptosis-related diseases." (PMID 39496543, 2024). "The data showed that knockdown of PIEZO1 markedly reduced pancreatic cancer cells proliferation ability (p=0.0064)." (PMID 35747124, 2022). "Since Piezo1 activation accelerates tumor growth and modulates the tumor microenvironment in pancreatic cancer, these findings suggest that Piezo channels, particularly Piezo1, have the potential to be novel therapeutic targets for drug design and treatment of GI tumors." (PMID 38379701, 2024). "High expression of Piezo1 in pancreatic cancer is associated with poor disease-free survival, and a noninvasive treatment strategy based on ultrasound stimulation of microbubbles induces mitochondrial dysfunction and apoptosis via Piezo1." (PMID 37762011, 2023).
glaucoma (8 papers, 2020 to 2025). Increased pressure in the eyeball due to obstruction of the outflow of aqueous humor. "Our findings demonstrate that the Piezo1 pathway is a crucial mediator of ferroptosis in TMCs, providing new insights into the pathogenic mechanisms of glaucoma, particularly POAG." (PMID 39466179, 2024). "This study aims to elucidate the role of Piezo1, a mechanosensitive molecule, in trabecular meshwork cells (TMCs) in the context of primary open angle glaucoma (POAG), a leading cause of irreversible visual impairment." (PMID 39466179, 2024). "Mechanosensitive ion channels, such as transient receptor potential cation channel subfamily V member 4 (TRPV4) and Piezo1, are postulated to be implicated in the development of glaucoma." (PMID 39337712, 2024). "Our study confirms that the Piezo1 e756del gain-of-function variant is a frequent polymorphism present in African descent individuals but is unrelated to examined differences in glaucoma phenotypes." (PMID 33149214, 2020). "Here, we investigated associations between a Piezo1 gain-of-function variant common in individuals of African descent with glaucoma-related phenotypes." (PMID 33149214, 2020). "The aim of this study was to investigate associations between Piezo1 variants and phenotypes relevant to glaucoma." (PMID 33149214, 2020). "In this study, we report our analyses of Piezo1 genotypic variants with glaucoma-related phenotypes in humans and phenotypic associations in mice." (PMID 33149214, 2020). "Analyzing Piezo1 variants in tandem with other known loci identified from prior GWAS analyses in glaucoma may yield further insights." (PMID 33149214, 2020). "Targeting the Piezo1 pathway offers new therapeutic potential for mitigating trabecular meshwork dysfunction and managing primary open angle glaucoma (POAG)." (PMID 39466179, 2024). "In summary, much work remains to continue developing our understanding of PIEZO1 and mechanotransduction in the pathophysiology and management of glaucoma and other conditions." (PMID 33149214, 2020). "Prior studies of the PIEZO1 mechanoreceptor have suggested a possible role in glaucoma pathophysiology." (PMID 33149214, 2020). "Given that Piezo1 regulates IOP in mice and PIEZO1 variants associate with primary open-angle glaucoma (POAG), we speculated that it plays a similar role in SC." (PMID 41279337, 2025). "Recent studies suggest that the expression and function of Piezo1 in TMCs may be related to the development of primary open-angle glaucoma (POAG)." (PMID 39466179, 2024). "Ongoing work is needed to elucidate the role of Piezo1-mediated mechanotransduction in glaucoma." (PMID 33149214, 2020). "Although we did not detect clear associations between Piezo1 gain-of-function mutations and glaucoma-related phenotypes, several important insights were generated." (PMID 33149214, 2020). "Several studies have suggested that Piezo1 may potentially have a role in glaucoma pathophysiology." (PMID 33149214, 2020). "The results of this study will help elucidate the role of Piezo1 in the pathogenesis of POAG and provide new perspectives and potential targets for the prevention and treatment of glaucoma." (PMID 39466179, 2024). "Taken together, although the specific mechanisms of Piezo1-mediated glaucoma pathogenesis and TRPV4-eNOS pathway remain unclear at the molecular level, it suggests potential for novel therapeutic target for glaucoma." (PMID 41561623, 2025). "Notably, studies have reported the expression of Piezo1 and Piezo2 in the astrocytes of the mouse ONH, with elevated levels of Piezo2 observed in rodent glaucoma model, specifically DBA/2J." (PMID 40873759, 2025). "First, a downregulation of Piezo1 expression was observed in the TM tissues of patients with POAG, suggesting a potential link between Piezo1 dysregulation and impaired mechanotransduction in the pathogenesis of glaucoma." (PMID 39466179, 2024).
glaucoma (continued). "With all of that said, our work suggests that increased Piezo1 activity in mice does not lead to glaucoma-like phenotypes." (PMID 33149214, 2020). "Thus, Piezo1 could acts as a regulator of intraocular pressure (IOP) within the conventional outflow pathway and could be a novel therapeutic strategy to modulate IOP in glaucoma patients." (PMID 33597646, 2021).
Hyperglycemia (8 papers, 2022 to 2026). An increased concentration of glucose in the blood. "In this study, we found that conditionally endothelial Piezo1-deficient transgenic mice ameliorated STZ-induced hyperglycemia by limiting oxidative stress and impairing endothelial barriers." (PMID 38702777, 2024). "Recent reports suggest that PIEZO1-mediated renal vasodilation is the key cause during acute kidney injury caused by acute hyperglycemia-associated hyperosmolarity." (PMID 39272994, 2024). "Surprisingly, we found that streptozotocin (STZ)-induced hyperglycemia was alleviated in Piezo1-deficient mice after 6 months." (PMID 38702777, 2024). "Collectively, these data indicate that the redistribution of PIEZO1 seen in diabetic db/db mouse islet β cells is a consequence of hyperglycemia and that T2D is associated with a reduction of plasmalemmal PIEZO1." (PMID 35869052, 2022). "Mechanistically, PIEZO1 in renal vascular endothelial cells is activated by hyperglycemia-associated hyperosmolarity, which in turn activates eNOS via CaMKII signaling and AKT signaling, ultimately contributing to the diastolic response of renal arteries and microvessels." (PMID 39272994, 2024). "In summary, our study revealed that Piezo1 is involved in high glucose-induced oxidative stress injury and aggravated endothelial dysfunction, which have great significance for alleviating endothelial damage caused by hyperglycemia." (PMID 38702777, 2024). "Moreover, the knockout of Piezo1 showed a thinner thoracic aortic wall, reduced tunica media damage, and increased endothelial nitric oxide synthase expression in transgenic mice, indicating the relief of endothelial damage caused by hyperglycemia." (PMID 38702777, 2024). "Piezo1, via CaMKII-mediated eNOS activation, induces hyperosmolarity-driven endothelial vasodilation during hyperglycemia, disrupts the medullary osmotic gradient, leading to excessive fluid and sodium excretion, and increases GFR in mice." (PMID 41480358, 2025). "Combining the results from in vitro and in vivo experiments, our research indicated Piezo1 activation under hyperglycemia and its adverse role in high glucose-induced oxidative stress injury, offering new insights into endothelial dysfunction in hyperglycemia." (PMID 38702777, 2024). "Recently, a study has revealed the activation of Piezo1 and its impact on phosphorylated Ca2+/CAMKII and phosphorylated eNOS in HUVECs, and found that the acute effects of Piezo1 activation inhibit vasodilation in small resistance arteries under hyperglycemia." (PMID 38702777, 2024). "Vascular endothelial-specific Piezo1 knockout mice were generated to investigate the effects of Piezo1 on Streptozotocin-induced hyperglycemia and vascular endothelial injury." (PMID 38702777, 2024). "Moreover, hyperglycemia activates PIEZO1 transcription in mature RBCs, and elevated PIEZO1 activity in RBCs, platelets, and neutrophils in patients with type 2 diabetes triggers prothrombotic cellular responses." (PMID 39012672, 2024). "Additionally, the inhibition of Piezo1 has been shown to protect against hyperglycemia-induced retinal light conduction damage in mice." (PMID 38702777, 2024). "Whether this Piezo1-activated enhanced host-defense pathway with induced expression of Nox4 is also active in hyperglycemia-induced Piezo1 upregulation remains to be investigated." (PMID 38541702, 2024). "The translocation of PIEZO1 into the nucleus in response to hyperglycemia suggests that PIEZO1 might be involved in transcriptional control in addition to serving as a mechanosensor in the plasma membrane." (PMID 35869052, 2022).